PLAC1 (placenta associated 1)
Diseases named in the same sentence as PLAC1 in open-access papers (continued):
Sharing a sentence is not in itself a finding about the gene and the disease.
breast cancer (continued). "In this study, our results showed that high Plac1 protein expression was markedly associated with HR status, advanced TNM stage, and metastatic axillary lymph nodes, which are known to be important features of breast cancer recurrence after resection, and generally have a poor prognosis." (PMID 29704427, 2018). "Therefore, more robust investigation into the function of Plac1 in breast cancer is necessary." (PMID 29704427, 2018). "Interestingly, we found previously that PLAC1 is a critical factor for breast cancer progression, as RNAi-mediated silencing of PLAC1 in MCF-7 and BT-549 breast cancer cells results in decreased cyclin D1 levels and induces a G1-S cell cycle block with nearly complete abrogation of proliferation." (PMID 24304549, 2013). "Only 3 tumor-reactive circulating CD8 T cell lines showed responses, which were limited to two CTA (PLAC1 and ACTL8) overlapping peptide pools, reiterating the challenge of finding relevant breast cancer antigens." (PMID 40730190, 2025). "Therefore, PLAC1 could be a specific target for breast cancer immunotherapy." (PMID 31952435, 2020). "The mechanism of our Plac1 study reveals that Plac1 physically interacts with Furin, which generates NICD fragments to inhibit the expression of PTEN, thereby promoting tumor progression in human breast cancer." (PMID 29704427, 2018). "Studies of PLAC1 expression in MCF7 and BT-549 breast cancer cell lines, including siRNA knockdowns, showed that PLAC1 expression is a vital component of cellular phenotypes including motility, migration, and invasion." (PMID 25180201, 2014). "To consolidate our data in vivo, we analyzed expression of PLAC1 and NCOA3 transcripts in 48 human primary breast cancer tissue samples." (PMID 24304549, 2013). "Our data introduce PLAC1 as novel target gene of NCOA3 in breast cancer, supporting the important role of both factors in breast cancer biology." (PMID 24304549, 2013). "The reason for such nearly universal PLAC1 expression in breast and uterine tumors may be that these cancers are far more hormone sensitive than are the others so far reported, and there is evidence from breast cancers that one of the PLAC1 promoters, P2, is estrogen responsive." (PMID 23935632, 2013). "New research on PLAC1 has indicated that it is well expressed in a versatile cancer cases, specifically in breast cancer, but not expressed in normal tissues, except testis." (PMID 31952435, 2020). "Thus, Plac1 increases the level of NICD to increase the invasion and metastasis of breast cancer cells through physically interacting with Furin." (PMID 29704427, 2018). "Although, co-expression of Plac1 and Cxcl1 in breast cancer tissue has not been reported, Cxcl1 expression in breast cancer biopsies was found to be elevated in metastases, and inversely related to ERα expression and relapse-free survival." (PMID 29632317, 2018). "In addition, multivariate Cox regression analysis revealed that Plac1 expression, LNM, HER2 status, and HR status were each recognized as independent prognostic factors for MFS in breast cancer." (PMID 29704427, 2018). "In other words, interaction of Plac1 and Furin may be sufficient to alter this pathway, further enhancing MMP2 and MMP9 protein levels to promote the invasion and metastasis of breast cancer cells." (PMID 29704427, 2018). "Taken together, our findings suggest that functional interaction between Plac1 and Furin enhances breast cancer invasion and metastasis and the Furin/NICD/PTEN axis may act as an important therapeutic target for breast cancer treatment." (PMID 29704427, 2018). "We detected selective recruitment of NCOA3 but not NCOA1 or NCOA2 to the PLAC1 promoter only in ERα-positive MCF-7 cells but not in ERα-negative SK-BR-3 breast cancer cells." (PMID 24304549, 2013). "In a first experiment, we analyzed expression of NCOA1, NCOA2 and NCOA3 in ERα-positive MCF-7 and ERα-negative SK-BR-3 breast cancer cells that both have been shown to express PLAC1 protein." (PMID 24304549, 2013).
breast cancer (continued). "Moreover, we demonstrate a relevant correlation of PLAC1 expression and NCOA3 overexpression in human breast cancer tissues restricted to the ERα-positive samples." (PMID 24304549, 2013). "In a previous study, we showed that ERα-signaling in breast cancer cells transactivates PLAC1 expression in a non-classical pathway." (PMID 24304549, 2013). "Our findings provide the basis to further dissect the role of PLAC1 in the ERα-signaling pathway in breast cancer and suggest PLAC1 as a novel target gene of NCOA3 in ERα-positive MCF-7 breast cancer cells supporting the role of both factors in breast cancer biology." (PMID 24304549, 2013). "Moreover, we observed a significant correlation of PLAC1 expression and NCOA3 overexpression in a cohort of ERα-positive breast cancer patients." (PMID 24304549, 2013). "However, Plac1 was not obviously associated with differentiation, gender, age, HER2 status, or tumor size in patients with breast cancer and OS (P < 0.152)." (PMID 29704427, 2018). "However, the roles of Plac1 expression in promoting breast cancer are not understood." (PMID 29704427, 2018). "Since we detect a significant correlation between NCOA3 overexpression and PLAC1 expression in ERα-positive breast cancer patients this adds to the relevance of understanding the role of PLAC1 in the NCOA3/ERα-signaling pathway and might open new therapeutic concepts for breast cancer." (PMID 24304549, 2013). "In contrast, PLAC1 transactivation was nearly abolished in cells lacking NCOA3, further confirming the important function of NCOA3 for E2/ERα-induced transactivation of PLAC1 in breast cancer cells." (PMID 24304549, 2013). "Furthermore, an association with various estrogen-dependent genes such as ANXA1, PIWIL2, CASP4, ESR1/ESR2, PLAC1, and SOCS2, has been shown in breast cancer—however, up to date, no such data concerning adenocarcinomas of the esophagogastric junction have been published." (PMID 31467538, 2019).
colorectal cancer (10 papers, 2013 to 2024). A primary or metastatic malignant neoplasm that affects the colon or rectum. "PLAC1, an X-linked trophoblast antigen, is ectopically expressed in a large set of cancer cell lines and several cancers, including melanoma, breast, cervical, prostate, ovary, liver, and colorectal cancers." (PMID 38707901, 2024). "Pursuing predictors of colorectal cancer, a growing number of studies have identified valuable biomarkers, such as Integrin beta-4 (ITGB4), Placenta-specific protein 1 (PLAC1), some miRNAs and lncRNAs." (PMID 35126454, 2021). "In colorectal cancer biopsies, higher levels of Plac1 were detected in 50% of stage III/IV disease in comparison to early stage disease, and Plac1-dependent cytotoxic T cell (CTL) activity correlated with overall survival." (PMID 29632317, 2018).
ovarian cancer (6 papers, 2014 to 2022). A primary or metastatic malignant neoplasm involving the ovary. "Elevated expression of placenta-specific protein 1 (PLAC1) is associated with the increased proliferation and invasiveness of a variety of human cancers, including ovarian cancer." (PMID 34577642, 2021). "PLAC1 is re-expressed in prostate, breast and ovary cancer and is a potential target for antibody–drug conjugate-based prostate cancer immunotherapy." (PMID 29950452, 2018). "In addition to placentae PLAC1 is expressed in a variety of solids including breast, endometrial, and ovarian cancers." (PMID 24757447, 2014).
prostate carcinoma (6 papers, 2017 to 2024). A carcinoma that arises from epithelial cells of the prostate gland. "In prostate cancer, Plac1 expression was positively associated with the Gleason score and negatively correlated with prostate‐specific antigen expression." (PMID 29704427, 2018). "In the current research, we explored the expression of the PLAC-1 molecule in prostate cancer stem cells (PCSCs) derived from the human PC-3 cell line." (PMID 38943028, 2024). "In vitro cytotoxic assay of anti-PLAC1-ADC against prostate cancer cell lines revealed consistent IC50 values in the lower nanomol range." (PMID 29042604, 2017). "We first confirmed Plac1 transcript expression in prostate cancer cell lines, LNCaP, DU145 and PC3 using RT-PCR." (PMID 29042604, 2017). "In flow cytometry analysis of prostate cancer cells, 2H12C12 recognized surface PLAC1 in 38.6% ± 7.03, 35.6% ± 4.03 and 30.4% ± 4.47 of LNCaP, DU145 and PC3 cells, respectively." (PMID 29042604, 2017). "Reactivity of the monoclonal anti-PLAC1 antibody, 2H12C12, with native target protein was tested in the next step by flow cytometry in prostate cancer cell lines." (PMID 29042604, 2017). "Having in mind the PLAC1 specificity as well as rapid internalization profile of the antibody upon engagement with its cell surface ligand in prostate cancer cells prompted us to address therapeutic potential of a drug-conjugated antibody." (PMID 29042604, 2017). "Our recent findings strongly support the idea of PLAC1 being as a potential immunotherapeutic target in prostate cancer (PCa)." (PMID 29042604, 2017). "Anti-PLAC1-ADC showed selective cytotoxicity against PLAC1-expressing prostate cancer cells and profoundly increased potency of cytotoxic drug payload suggesting PLAC1 as a highly promising therapeutic target for ADC-based cancer immunotherapy." (PMID 29042604, 2017). "In order to visualize the routing of anti-PLAC1 antibody in prostate cancer cells, LNCaP cells were pulsed with the antibody for different times at 37 °C, then fixed and stained with FITC-conjugated secondary antibody." (PMID 29042604, 2017). "In spite of the wide expression pattern of PLAC1 in variety of cancers, prostate cancer seems to be the prototype model for investigation of potential therapeutic effects of anti-PLAC1-based nanomedicine due to its high prevalence and differential expression of PLAC1 in PCa8,33." (PMID 29042604, 2017). "Anti-PLAC1-ADC induced apoptosis in human primary prostate cancer cells and prostate cell lines." (PMID 29042604, 2017). "Some scholars found in the study of prostate cancer that PLAC1 has high reactivity in prostate cancer cells, and antibody-drug conjugates based on anti PLAC1 may pave the way for the development of more reliable, efficient and new immunotherapy for prostate cancer patients." (PMID 37568074, 2023). "To pursue potential application of anti-PLAC1 antibodies for cancer immunotherapy, we developed an anti-PLAC1-ADC and assessed its potential efficacy in three human prostate cancer cell lines, namely LNCaP, DU145, and PC3." (PMID 29042604, 2017). "Cytotoxic effect of anti-PLAC1-ADC was further assessed by apoptosis assay in LNCaP and also in human primary prostate cancer cells." (PMID 29042604, 2017). "The Anti-PLAC1 clone, 2H12C12, showed high reactivity with recombinant PLAC1 and selectivity recognized PLAC1 in prostate cancer cells but not in LS180 cells, the negative control." (PMID 29042604, 2017). "After a 48 h incubation period, anti-PLAC1-ADC efficiently induced cell death in a great proportion of prostate cancer cells, while no apparent cytotoxicity was observed in PLAC1 negative LS180 cell line." (PMID 29042604, 2017).
colon cancer (4 papers, 2014 to 2023). "Analysis of PLAC1 expression in selected primary tumor tissues revealed low expression in individual lung and colon tumors but considerably higher expression in a breast tumor." (PMID 24912876, 2014). "It is reported that the high expression of PLAC1 in colon cancer can be used as a predictor of poor prognosis, and it may enhance the potential of liver metastasis by activating PI3K/Akt/NF kB signaling pathway." (PMID 37568074, 2023).
gastric cancer (4 papers, 2011 to 2020). A primary or metastatic malignant neoplasm involving the stomach. "On the other hand, PLAC1, a recently described X-linked gene exhibiting expression restricted to the placenta, is also expressed in a wide variety of human cancers, including gastric cancer." (PMID 21304604, 2011). "Over-expression of miR-126 was found to inhibit placenta-specific 1(Plac1) and further increase the viability of gastric cancer by targeting sex-determining region Y-box 2 (SOX2) as oncogene." (PMID 24312276, 2013). "siRNA- and miR-126-mediated SOX2 knockdown experiments revealed that miR-126 positively regulated PLAC1 expression through suppression of SOX2 expression in gastric cancer cells." (PMID 21304604, 2011). "We next performed microarray analysis after SOX2 over-expression in a gastric cancer cell line, and found that expression of the placenta-specific 1 (PLAC1) gene was significantly down-regulated by SOX2 over-expression." (PMID 21304604, 2011). "Furthermore, Pre-miR-126 over-expression promoted anchorage-dependent and -independent growth of gastric cancer cells in vitro, and increased oncogenic PLAC1 expression in a gastric cancer cell line." (PMID 21304604, 2011). "Taken together, our results indicate that miR-126 is a novel miRNA that targets SOX2, and PLAC1 may be a novel downstream target gene of SOX2 in gastric cancer cells." (PMID 21304604, 2011). "Expression of KRT6A and PLAC1 was significantly changed by both SOX2 over-expression and knockdown, suggesting that SOX2 is the critical regulatory factor for these two genes in gastric cancer cells." (PMID 21304604, 2011).
hepatocellular carcinoma (4 papers, 2013 to 2023). A malignant tumor that arises from hepatocytes. "Accumulating evidence suggests that enhanced PLAC1 expression is closely associated with the progression of human cancer; accordingly, the upregulated expression of PLAC1 in human hepatocellular cancer (HCC) was found significantly correlated with metastasis of HCC." (PMID 36835024, 2023). "Also, in hepatocellular carcinoma and gastric adenocarcinoma patients, Plac1 overexpression correlated with poor prognosis." (PMID 29704427, 2018).
endometrial cancer (3 papers, 2013 to 2025). Primary or metastatic malignant neoplasm involving the endometrium (mucous membrane that lines the endometrial cavity). "We have shown both through conventional RT-PCR and SYBR Green qPCR assays that the gene encoding the oncoplacental protein PLAC1 is expressed in endometrial cancer cell lines and in all three of the most common endometrial tumors." (PMID 23935632, 2013). "Previous studies have shown that pregnancy reduces the risk of endometrial cancer by reducing estrogen exposure; however, it has been reported that some pregnancy-related factors, such as placental growth factor (PlGF) and placenta-specific protein 1 (PLAC-1), are associated with endometrial cancer." (PMID 30921436, 2019). "First, it has been reported that increased plasma concentrations of hormones such as GnRH and PlGF (secreted by the placenta), and proteins such as IGFBP1 and PLAC-1 are correlated to the development of endometrial cancer." (PMID 30921436, 2019). "Our own data show that P1 accounts for significantly more PLAC1 message in all of the endometrial tumors, but there is a mixture of P1-driven and P2-driven messages in the endometrial cancer cell lines derived from adenocarcinomas." (PMID 23935632, 2013). "Here, we demonstrate ubiquitous PLAC1 expression in a panel of endometrial tumors as well as in endometrial cancer cell lines." (PMID 23935632, 2013). "While the function of the two PLAC1 promoters and their regulation are as yet unknown, overall expression data suggest that PLAC1 may serve as a biomarker for endometrial cancer as well as a potential prognostic indicator." (PMID 23935632, 2013). "PLAC1 transcript was detected to varying degrees among the seven endometrial cancer cell lines." (PMID 23935632, 2013). "In addition to ubiquitous PLAC1 expression in the tumor panel, of the seven endometrial cancer cell lines examined here, only the five cell lines derived from endometrioid adenocarcinomas, Ishikawa H, ECC-1, KLE, Hec50co, and AN3CA, evidenced appreciable PLAC1 expression." (PMID 23935632, 2013).
head and neck squamous cell carcinoma (3 papers, 2016 to 2025). A squamous cell carcinoma that arises from any of the following anatomic sites: lip and oral cavity, nasal cavity, paranasal sinuses, pharynx, larynx, and salivary glands. "screen genes in the CTAs family and find Plac1 is specifically expressed in head and neck squamous cell carcinoma (HNSCC) cells." (PMID 40056047, 2025). "Five single‐cell and two bulk RNA‐seq datasets are integrated to screen genes in the CTAs family, revealing that Placenta specific protein 1 (Plac1) is specifically expressed in head and neck squamous cell carcinoma (HNSCC) cells." (PMID 40056047, 2025).
Infertility (3 papers, 2013 to 2014). "We reported that women can become sensitized to the PLAC1 antigen during pregnancy and the presence of anti-PLAC1 antibodies may be associated with infertility and/or recurrent pregnancy loss." (PMID 24600606, 2014). "Recently, we reported that women can become sensitized to the PLAC1 antigen during pregnancy and the presence of anti-PLAC1 antibodies may be associated with infertility and/or recurrent pregnancy loss." (PMID 23840959, 2013). "There is also evidence that high levels of anti-PLAC1 antibody may be involved in some cases of unexplained infertility." (PMID 24757447, 2014).
lymph node metastasis (3 papers, 2018 to 2023). "We have shown that Plac1 expression positively correlates with clinical stage, lymph node metastasis, hormone receptor status, and overall patient survival." (PMID 29704427, 2018). "The CRC patients with liver metastasis (low differentiation and lymph node metastasis) had significantly higher positive expression of PLAC1 than these with moderately high differentiation and no lymph node metastasis (P < 0.05)." (PMID 37568074, 2023).
stomach adenocarcinoma (3 papers, 2018 to 2022). "PLAC1 nuclear localization has also been reported in stomach adenocarcinoma 24 and in colorectal adenocarcinoma 22 tissues." (PMID 32153735, 2020).
breast tumor (2 papers, 2014 to 2025). "PLAC1-specific T cells with the ability to kill breast tumor lines were previously found in healthy donors." (PMID 40730190, 2025). "Lastly, expression of PLAC1 was found to be higher in some primary breast tumors compared to normal adjacent tissues." (PMID 24912876, 2014).